NLRP3 (NLR family pyrin domain containing 3)
Diseases named in the same sentence as NLRP3 in open-access papers (continued):
Sharing a sentence is not in itself a finding about the gene and the disease.
kidney diseases (continued). "Therefore, in this paper, we review the interplay between autophagy and the NLRP3 inflammasome and the mechanisms in different renal diseases to provide ideas for relevant basic research in the future." (PMID 34884572, 2021). "The interplay between autophagy and NLRP3 inflammasome plays a vital role in renal diseases." (PMID 34884572, 2021). "The current studies have shown that there is a negative regulation between autophagy and NLRP3 in renal diseases, and whether there is a positive regulation remains to be clarified." (PMID 34884572, 2021). "Whether autophagy/NLRP3 inflammasome plays different roles in different times of renal disease, such as early, middle, and late stage, needs further study." (PMID 34884572, 2021). "Whether targeted autophagy/NLRP3 inflammasome has side effects in the treatment of renal diseases remains to be clarified." (PMID 34884572, 2021). "The inhibitors of NLRP3 have been shown to work particularly well for kidney disease." (PMID 34944017, 2021). "However, the relationship between exosomes and NF-κB/NLRP3 pathway in renal diseases particularly in IgAN remains concealed." (PMID 32765277, 2020). "The NLRP3 inflammasome plays a role in the pathogenesis of renal diseases, including AKI." (PMID 32131850, 2020). "Glomerular dysfunction associated with inflammatory microenvironments may benefit from inhibiting NLRP3 inflammasomes, and many compounds have shown this effect in murine models of kidney diseases." (PMID 31427885, 2019). "Additionally, inflammasome-independent NLRP3 plays a pivotal role in kidney disease by regulating apoptosis, fibrosis, and mitochondrial injury in cases of direct injury to renal TECs and fibroblasts." (PMID 31694192, 2019). "Recent studies have suggested that NLRP3 inflammasome and downstream cytokines contribute to several types of kidney disease, including crystalline nephropathy, obstructive nephropathy, and obesity-related kidney diseases." (PMID 31572210, 2019). "Recently, several studies have suggested that NLRP3 could mediate podocyte dysfunction in several different kidney diseases." (PMID 31796125, 2019). "Notably, the important role of the NLRP3 inflammasome in modulating kidney inflammation has been confirmed in different renal disease models including I/R injury." (PMID 29500339, 2018). "We have previously shown that deletion of Pr2x7 gene attenuated renal disease in mice fed a HFD and that this was associated with blunted upregulation of the NLRP3 inflammasome components NLRP3, ASC, procaspase-1, pro-IL-1β, and pro-IL-18 and reduced the formation of mature caspase-1." (PMID 29270247, 2017). "Herein, we hypothesized that activation of NLRP3 inflammasome contributes to the pathogenesis of IgAN and targeting the inflammasome may be beneficial for the treatment of the renal disease." (PMID 28117341, 2017). "An increasing amount of evidence suggests that UA-induced inflammatory responses are the central mechanisms of tubular injury in hyperuricemic rodents and that the activation of NLRP3 and its mediating effects on inflammatory responses play key roles in various renal diseases." (PMID 29358971, 2017). "Targeting mitochondria and/or NLRP3 inflammasome may be a novel therapeutic strategy for the treatment of RAS activation-related kidney disease." (PMID 27509058, 2016). "Furthermore, the analysis of NLRP3 using a purely human system in vitro and in vivo is the first step in the bench to the bedside knowledge translation of NLRs in human kidney disease." (PMID 27093923, 2016). "NLRP3 is the best-characterized inflammasome and is of special interest in renal diseases." (PMID 27819323, 2016). "Collectively, these data suggest that the biology of the NLRP3 in the kidney may differ from the canonical inflammasome pathway described in macrophages and other non-renal disease models that rely primarily caspase-1 activation and cytokine maturation." (PMID 27093923, 2016).
kidney diseases (continued). "Thus far, nothing is known about the role of NLRP3 in human renal diseases or solid organ transplantation." (PMID 27819323, 2016). "Currently, it is unknown if NLRP3 SNPs are related to human renal diseases or patient outcome after solid organ transplantation." (PMID 27819323, 2016). "Treatment with TUDCA markedly attenuated kidney disease and decreased Nlrp3 inflammasome activation, indicating that the Nlrp3 inflammasome may be downstream of the ER stress pathway in Aldo-induced kidney disease." (PMID 27721575, 2016). "However, despite the increasing number of reports describing a role for NLRP3 in animal renal injury models, the characterization of NLRP3 in the context of human kidney diseases remains largely unexplored." (PMID 27093923, 2016). "One of the primary goals of this study was to translate NLRP3 knowledge to human kidney disease." (PMID 27093923, 2016). "The role of NLRP3 inflammasome activation in human renal disease is still uncertain." (PMID 24450291, 2014). "Thus, attenuating the inflammatory response by modulating the NLRP3 complex has become a new therapeutic strategy in the context of kidney diseases, especially those related to DM, aiming to reduce disease progression by reducing the inflammatory response mediated by the NLRP3 complex." (PMID 39412512, 2024). "In addition to the key role of the NLRP3 inflammasome in immune cells, previous studies have also demonstrated inflammasome activation in nonimmune cells in the kidney, such as podocytes and renal tubular epithelial cells, in kidney disease." (PMID 38720901, 2024). "Moreover, the NLRP3 inflammasome can modulate the activation and function of other inflammatory signaling pathways, such as NF-κB and mitogen-activated protein kinases (MAPKs), amplifying the inflammatory cascade in renal diseases." (PMID 37371054, 2023). "In this scenario, in patients affected by kidney disease the presence of functional SNPs of NLRP3 pathway-related genes, alone or in combination, could influence the activation of the NLRP3 machinery, strongly contributing to increase/sustain renal inflammation and fibrosis, leading to CKD/ESRD." (PMID 36835594, 2023). "Moreover, NLRP3-augmented intrarenal expression among non-diabetic patients with kidney disease has been found to be associated with worse renal function, suggesting that the NLRP3 inflammasome contributes to CKD." (PMID 35204237, 2022). "Consequently, various mechanisms may be involved in the pathogenesis of renal diseases mediated by the NLRP3 inflammasome." (PMID 34904012, 2021). "However, the role of NLRP3 inflammasome in human kidney disease is still indeterminate." (PMID 33215255, 2021). "In the lysosome rupture model, the NLRP3 inflammasome is thought to be activated upon sensing the large molecules such as uric acid and cholesterol leading to the lysosome rupture; this reflects the key role of inflammasome in kidney disease and atherosclerosis." (PMID 32175320, 2020). "This suggests the involvement of the NLRP3–ASC–caspase-1 axis in the occurrence and progression of kidney disease." (PMID 41357229, 2025). "A study revealed that both mRNA and protein expressions of NLRP3 and AIM2 were detected in renal biopsy samples obtained from patients with kidney disease." (PMID 38740765, 2024). "Inhibitors of the NLRP3 inflammasome, such as MCC950 and CY-09, have been shown to ameliorate renal injury and improve kidney function in various animal models of kidney disease." (PMID 37371054, 2023). "The NLRP3 inflammasome has also been shown to be involved in various CKD-related conditions, as demonstrated in different experimental models of kidney disease." (PMID 34680443, 2021). "Several studies have showed that inflammasomes are closely related to kidney diseases, especially the NOD-, LRR- and pyrin domain-containing 3 (NLRP3) inflammasome, which play a role in regulating kidney inflammation and fibrosis." (PMID 32175320, 2020).
kidney diseases (continued). "Several studies have showed that inflammasomes are closely related to kidney diseases, including the NOD- and LRR-pyrin domain-containing 3 (NLRP3) inflammasome, especially NLRP3, which play a role in regulating kidney inflammation and fibrosis." (PMID 32655761, 2020). "There is a strong relationship between NLRP3 inflammasome and TXNIP in the development of kidney diseases." (PMID 29849929, 2018). "NLRP3 (NOD-like receptor family, pyrin domain containing 3) is a member of the inflammasome family and is of special interest in renal disease." (PMID 27819323, 2016). "However, the role of NLRP3 in human renal disease is completely unknown." (PMID 27819323, 2016). "In conclusion, we herein reported that the NLRP3 inflammasome exerted primary effects on CI-AKI by modulating the cell apoptosis, thus provided a novel therapeutic target for kidney diseases, particularly for the treatment of CI-AKI." (PMID 27721494, 2016). "Notably, nod-like receptor protein 3 (NLRP3), an inflammatory regulator, has been found to be activated in mouse models of CKD and AKI, as well as in human kidney diseases." (PMID 38907332, 2024). "In this review, we focus on the NLRP3 inflammasome in kidney diseases both in canonical and non-canonical signaling pathway, and provide an update on its roles in kidney disease and discuss their potential therapeutic effects for the future application." (PMID 32175320, 2020). "Further investigations are needed to elucidate the effect of NLRP3 inhibitors on nonimmune renal cells in NLRP3-related kidney diseases." (PMID 31694192, 2019). "Although inflammasome-independent NLRP3 has been suggested to be related with mitochondrial injury in non-immune cells, the role of inflammasome-independent NLRP3 in kidney disease has not been clarified yet." (PMID 30483252, 2018). "We previously demonstrated increased NLRP3 mRNA in kidney biopsies from a variety of nondiabetic kidney diseases including IgAN6." (PMID 27093923, 2016). "The relatively higher expression of CASP4, CASP11, and GBPs compared to CASP1, PYCARD, and NLRP3, however, may suggest a more prominent role of non-canonical versus canonical inflammasome activation contributing to kidney disease." (PMID 38838223, 2024). "Nlrp3 also has canonical and noncanonical roles in models for other kidney disease." (PMID 36837885, 2023). "However, although many kinds of biological inhibitors against the NLRP3 inflammasome have been developed, at present, their efficacy and safety for kidney diseases have not been defined." (PMID 36835594, 2023). "Blockade of IL-1β, the end product of an activated NLRP3 inflammasome, could not mitigate kidney diseases." (PMID 37685978, 2023). "However, the mechanisms involved in the interaction between autophagy and NLRP3 inflammasome in renal disease are not fully clear." (PMID 34884572, 2021). "In the rat contrast-induced nephropathy model, ioversol induced kidney morphology changes, with increases on SCr and BUN contents, elevated levels of IL-1β and IL-18, upregulated expressions of lncRNA XIST, NLRP3, ASC, and cleaved caspase-1, and decreased miR-133a-3p mRNA expression." (PMID 33912556, 2021). "However, the detailed mechanisms by which NLRP3 is involved in the pathogenesis of kidney diseases are not yet precise." (PMID 31694192, 2019). "However, blockade of IL-1β, the end product of the activated NLRP3 inflammasome, failed to mitigate kidney disease, whereupon interest concerning inflammasome-independent NLRP3 increased." (PMID 31694192, 2019). "NLRP3 inflammasome is not limited by traditional microbial stimuli of innate immunity and its connection with autophagy, fibrosis, and pro-inflammatory cytokines has broader implications for a variety of kidney disease." (PMID 29371912, 2017).
kidney diseases (continued). "In addition to the inflammasome-dependent pathway, NLRP3 possesses biologic functions in various kidney diseases without forming an inflammasome, which is called the inflammasome-independent pathway of NLRP3, the exact mechanisms of which have not yet been revealed." (PMID 37685978, 2023). "Interestingly, although research on the mechanism of probiotics in the treatment of kidney diseases is still lacking, several studies have reported that probiotics, especially Bifidobacterium spp., could inhibit the expression of the NLRP3 gene." (PMID 36038927, 2022). "Although based on in-vitro studies, NLRP3 inflammasome may have a role in the pathogenesis of renal diseases via overexpression of proinflammatory cytokines including IL-1β and IL-18, several pieces of evidence show that the NLRP3 effect may be independent of pro-inflammatory cytokine production." (PMID 34904012, 2021). "Furthermore, given the vast differences in pathogenesis, whether or not NLRP3 represents a similar biomarker in other forms of kidney disease cannot be determined from these results." (PMID 27093923, 2016).
bacterial infection (137 papers, 2011 to 2026). "NEDD4L-deficient cells showed increased GSDM activation, IL-1β release and were significantly more susceptible to cell death induced by NLRP3 agonists, cytotoxic agents, and bacterial infection." (PMID 41261204, 2025). "It would be of interest to perform functional assays to confirm if functions remain conserved, for example, both human and mouse GBP5 have been implicated in the NLRP3 activation upon bacterial infection." (PMID 38357541, 2024). "The NLRP3 (NLR family pyrin domain containing 3) inflammasome is implicated in inflammatory conditions, such as trauma, atherogenesis, and bacterial infection." (PMID 37628850, 2023). "These diseases have been shown to be caused by either bacterial infections or aseptic inflammation, suggesting the potential activation of NLRP3 inflammasome." (PMID 33679781, 2021). "The IFN signaling eventually downregulates the NLRP3 inflammasome (that is normally activated by the viral orf3a) which is downregulated in DS, leading to higher susceptibility to secondary bacterial infections." (PMID 33479353, 2021). "The indication that up-regulated NLRP3 inflammasome is implicated in the increased vulnerability of living donor steatotic livers to I/R injury and bacterial infection in LT is reflected in clinical hepatic resection practice." (PMID 31547621, 2019). "A clinical study of 190 patients, which focused on post-transplantation bacterial infection identified donor gene polymorphisms involved in NLRP3 inflammasome activation as representing a risk of bacterial infection prior to surgery." (PMID 31547621, 2019). "CEACAM1 is a receptor on neutrophils, and CEACAM1 negatively regulates both NLRP3 inflammasome activation and immune response and has been found to increase the susceptibility of bacterial infection." (PMID 31093495, 2019). "NLRP3 has recently been implicated in necrotic death in macrophages triggered by bacterial infections." (PMID 21740493, 2011). "Nevertheless, the mechanisms predisposing ALD patients to bacterial infections and the role of the NLRP3 inflammasome in the intestinal epithelial barrier in ALD remain unclear." (PMID 39605303, 2024). "MiRNA-142 from macrophage-derived EVs could also suppress NLRP3 inflammasome activation and bacterial infection-associated lung inflammation." (PMID 35463634, 2022). "Secondly, bacterial infection leads to the release of several danger signaling molecules termed damage-associated molecular patterns (DAMPs), which constitute an additional triggering signal for the assembly of NLRP3 inflammasomes." (PMID 27980220, 2017). "Next, to examine whether VopQ-induced autophagy suppresses the NLRC4 inflammasome, we performed the short hairpin RNA (shRNA) knockdown of ATG5, one of the components of autophagy in NLRP3-deficient BMMs and assessed inflammasome activation upon bacterial infection." (PMID 23357873, 2013). "Research has found that the activation of NLRP3 is triggered not only by ROS but also influenced by various other factors, such as ATP, intracellular calcium ion concentration, bacterial infections, and other danger signals." (PMID 41513612, 2026). "This interaction promotes the K27-linked polyubiquitination of AIM2, NLRP3, and NLRC4, which are essential for inflammasome assembly, ASC speck formation, and IL-1β production upon bacterial infection." (PMID 40307577, 2025). "During viral and bacterial infections in human myeloid cells, NLRP3 was tightly linked to the upstream cGAS-STING pathway, inducing NLRP3 inflammasome activation and coordinating lysosomal cell death (LCD) in a K+ efflux-dependent manner." (PMID 38195584, 2024). "In conjunction with previous studies, IL-22 has been shown to inhibit the activation of the NLRP3 inflammasome by suppressing the synthesis of NLRP3 and Caspase-1 proteins, thereby attenuating mammalian bacterial diseases and tissue injury." (PMID 39211040, 2024). "Moreover, NLRP3 may contribute to bone loss caused by bacterial infection." (PMID 38994035, 2024).